SNORA80B (small nucleolar RNA, H/ACA box 80B)
Synonyms: ACA67B
Gene: Small nucleolar RNA gene on chromosome 2 (10,446,714 to 10,446,849, reverse strand). Ensembl gene ENSG00000206633.
Gene Ontology:
Biological process: RNA processing
Cellular component: nucleolus
Homologues: Orthologues: chimpanzee SNORA80B (100% identical), macaque SNORA80B (97% identical). Paralogues in human: SNORA80A (92% identical), SNORA80D (90% identical), SNORA80C (88% identical), SNORA80E (75% identical).